PALB2 (partner and localizer of BRCA2)
Diseases named in the same sentence as PALB2 in open-access papers (continued):
Sharing a sentence is not in itself a finding about the gene and the disease.
pancreatic cancer (continued). "Except for MSH3, the rest of the germline mutant genes in non-BRCA carriers with TNBC were involved in the HRR pathway, including BLM, PALB2, NBN, RAD51C, and RAD51D, with the mutation rate of 9.26% (5/54), which increased the risk of other cancers, such as PLAB2 for pancreatic cancer." (PMID 33194720, 2020). "Thus, we generated mouse models of pancreatic cancer by inactivation of Palb2, Brca1 or Brca2 genes specifically in the pancreas and compared the resulting tumor latencies, histo-pathologies, anticancer drug responses and immune cell infiltration." (PMID 31877165, 2019). "To determine if the role of PALB2 as a linker between BRCA1 and BRCA2 is critical for BRCA1/2-mediated tumor suppression, we generated Palb2 mouse pancreatic cancer models and compared tumor latencies, phenotypes and drug responses with previously generated Brca1/2 pancreatic cancer models." (PMID 31877165, 2019). "These preclinical results indicate that DNA damaging agents are effective and could be particularly useful in the treatment of PALB2-, BRCA1- or BRCA2- deficient pancreatic tumors, which is reminiscent of human cancers defective for ‘BRCAness’." (PMID 31877165, 2019). "The exome sequencing of a large set of patients with familial pancreatic cancer demonstrated that inherited pancreatic cancer is highly heterogeneous: in these patients, germline mutations of ATM, BRCA2, CDKN2A and PALB2 are observed, all elevating risk of developing pancreatic cancer." (PMID 29156578, 2017). "Although chronic pancreatitis is an important risk factor for pancreatic cancer development most of the mutated genes found to contribute to pancreatic cancer susceptibility when defective are classic tumor suppressor genes, such as BRCA2, ATM, PALB2, p16, and STK11." (PMID 28881607, 2017). "After identifying bi-allelic inactivation of PALB2 in a tumour from a familial pancreatic cancer patient, Jones and colleagues investigated germline PALB2 variation in 96 probands with a family history of pancreatic cancer and identified truncating mutations in three individuals." (PMID 24949998, 2014). "Although several important and high-penetrance genes associated with increased risk of pancreatic cancer have been identified, including BRCA2 and PALB2, it is clear that most cases of pancreatic cancer that demonstrate familial clustering are not explained by known genetic syndromes." (PMID 24624093, 2014). "Mutations in the high penetrance genes such as BRCA2, PALB2, p16/CDKN2A, PRSS1, SPINK1, and STK11 correlate with a very high lifetime risk of developing pancreatic cancer and may cause as many as 10% of pancreatic cancers in the US." (PMID 24883056, 2014). "High sensitivity of PALB2-deficient xenografted pancreatic tumor to mitomycin C and cisplatin but not to gemcitabine." (PMID 21819606, 2011). "Screening for pancreatic cancer with an annual MRI and/or endoscopic ultrasound from the age of 50 (or 5–10 years younger than the affected relative) can also be considered, when at least one first- or second-degree, presumably PALB2-positive relative develops exocrine pancreatic cancer." (PMID 38817905, 2024). "As described in the pancreatic cancer section, in this phase 2 trial, the ORR for rucaparib in germline BRCA2 (41%) was similar to that in germline PALB2 (50%) and somatic BRCA2 (50%), suggesting a similar benefit with PALB2 mutations, although the limitation was that numbers were low." (PMID 39796639, 2024). "The estimated absolute risks for pancreatic cancer in ATM PTV carriers (11% in males and 8% in females by age 85) are notably higher than for other major pancreatic susceptibility genes including BRCA2, CDK2NA, and PALB2, although the confidence limits are wide." (PMID 39209703, 2024).
pancreatic cancer (continued). "Based on the available literature, it is estimated that 17 to 25% of pancreatic cancer harbor somatic PVs in one of the genes involved in DDR, mainly those implicated in homologous recombination DNA damage response and repair (HR), such as BRCA1, BRCA2, ATM, PALB2, ATRX, and RAD51." (PMID 35563100, 2022). "However, only 21% of pancreatic cancer patients are sensitive to platinum-based chemotherapy, and the objective response rate to platinum-based regimens is only ~50%, even among pancreatic cancer patients with germline BRCA or PALB2 mutations." (PMID 35264742, 2022). "Recently, the ACMG published a guideline for patients with germline variants in PALB2, in which risk-reducing mastectomy is an option to be considered to reduce BC risk as well as to include surveillance for pancreatic cancer; however, oophorectomy is not recommended for patients below 50 years." (PMID 35451682, 2022). "Pancreatic cancer patients with BRCA1/2 and PALB2 mutations may benefit from MMC treatment." (PMID 36359225, 2022). "Additionally, for clinical trials evaluating platinum-based chemotherapy in all-comers with pancreatic cancer, special attention should be given to patients with germline mutations in BRCA or PALB2 given the impact of these genetic changes on response to chemotherapy." (PMID 31787751, 2020). "In pancreatic cancer, cases with BRCA2/PALB2 germline alterations display higher IFN responses, encompassing both type I (α/β) and type II (γ)." (PMID 40830526, 2025). "Since then, additional genes involved in the HR-pathway, such as PALB2, ATM, and CHECK2, have been identified, and a clear link between HRD and breast, ovarian, prostate, and pancreatic cancer has been established." (PMID 40988318, 2025). "Currently, germline panels for PALB2 and BRCA1/2 are utilized for breast, ovarian, and pancreatic cancer." (PMID 40948682, 2025). "For PALB2 and ATM carriers, pancreatic cancer screening can be considered starting at age 50 or earlier if there is a relevant family history." (PMID 40649708, 2025). "Of the 6474 patients with pancreatic cancer, 27 (0.4%) had BRCA1 alterations, 108 (1.7%) had BRCA2 alterations, 76 (1.2%) had germline ATM alterations, 25 (0.4%) had PALB2 alterations, and 27 (0.4%) had CHEK2 alterations." (PMID 40361359, 2025). "In contrast to KPC animals (n = 28, T50 = 24.6 weeks), Palb2-KPC, Brca1-KPC or Brca2-KPC respectively developed PDAC with a much shorter pancreatic tumor-free median survival of 10.1, 11.9 and 13.7 weeks, respectively." (PMID 31877165, 2019). "Among 190 pancreatic cancer patients, the positive yield was 10.5% (n = 20), and positive results were most commonly identified in ATM (40.0%; 8/20), BRCA2 (25.0%; 5/20), and PALB2 (15.0%; 3/20)." (PMID 26681312, 2016). "Several theoretically “actionable” aberrations exist in pancreatic cancer including, but not limited to, KRAS, CDKN2A, ARID1A, BRCA, PALB2, PIK3CA, BRAF and so forth." (PMID 25714017, 2015). "Furthermore, recognising the role of PALB2 in the DNA repair pathway is increasingly important, particularly as updated treatment guidelines now recommend assessing this gene when deciding whether patients with breast or pancreatic cancer may benefit from PARP inhibitor therapy." (PMID 41049353, 2025). "The risk for pancreatic cancer in individuals with pathogenic variants of BRCA1, BRCA2, PALB2, or ATM but without a history of pancreatic cancer has not been elucidated." (PMID 35163129, 2022). "The lifetime risk of developing OC is 3–5% for PALB2 GPV carriers, whereas that for pancreatic cancer is 5–10%; however, the absolute risks are not well estimated and are limited." (PMID 35806485, 2022).
pancreatic cancer (continued). "Thus, we expected chromosomal instability and hypersensitivity of primary tumor cells isolated from Palb2-KPC, Brca1-KPC, or Brca2-KPC pancreatic tumors to DNA damaging agents." (PMID 31877165, 2019). "Therefore, using our Palb2-KPC mouse model, we tested whether LOH is required for pancreatic tumor development in Palb2flox/+; KPC animals." (PMID 31877165, 2019). "However, we cannot rule out a higher PALB2 prevalence in series with more pancreatic cancer index cases." (PMID 23935836, 2013). "Two PALB2-positive patients did not have a family history of breast, ovarian, pancreatic, or colorectal cancer, whereas two other patients had a strong family history (at least three first- or second-degree relatives diagnosed with breast, ovarian, or pancreatic cancer)." (PMID 33120919, 2020). "A recently published study combining two parallel phase 2 clinical trials assessed olaparib monotherapy in 24 patients with previously treated pancreatic cancer and non-BRCA HR gene alterations (somatic BRCA, germline or somatic ATM, PALB2, ARID1A, PTEN, RAD51, CCNE and FANCB)." (PMID 34572943, 2021).
Fanconi anemia (113 papers, 2009 to 2025). Fanconi anemia (FA) is a hereditary DNA repair disorder characterized by progressive pancytopenia with bone marrow failure, variable congenital malformations and predisposition to develop hematological or solid tumors. "The same frameshift mutation in PALB2 has been reported for a patient with Fanconi anemia, and talazoparib has subsequently been shown to be active for patients with germline PALB2 mutations." (PMID 39510293, 2024). "Biallelic mutations in the PALB2 are known to cause Fanconi anemia of complementation group N (OMIM# 610832)." (PMID 37623222, 2023). "Homozygous mutations of PALB2 cause Fanconi anemia, a rare recessive chromosomal breakage syndrome characterized by physical abnormalities, bone marrow failure and a high risk of malignancy." (PMID 34461861, 2021). "Constitutional biallelic variants in PALB2 can cause Fanconi Anaemia associated with DNA repair deficiency." (PMID 33854214, 2021). "A PALB2-deficient Fanconi anemia cell line showed impaired RAD51 foci formation and hypersensitivity to MMC treatment." (PMID 32185139, 2020). "Biallelic PALB2 pathogenic variants were showed to cause Fanconi anemia, similar to BRCA1 and BRCA225." (PMID 31937788, 2020). "Despite PALB2 biallelic mutations being associated with Fanconi Anemia, heterozygous variants are known to confer a moderate risk to BC." (PMID 32039725, 2020). "Like BRCA proteins, PALB2 is an essential mammalian protein linked to a similar spectrum of cancers and Fanconi anemia." (PMID 31017574, 2019). "WES revealed that HMCLs displayed frequent mutations in Fanconi anemia genes (PALB2 [12%], FANCI [12%], FANCA [9%], FANCD2 [9%], BRCA2 [9%]) as well as in helicases (such as RECQL4, 15%, and BLM, 15%) and epigenetic modifiers (e.g., TET2, 15% and SETD2, 6%)." (PMID 30545397, 2018). "PALB2 is a pivotal player of the DNA damage repair; especially by its participation on the Fanconi anemia (FA) pathway; biallelic PALB2 mutations cause the N subtype of Fanconi anemia (FA-N)." (PMID 28858227, 2017). "These domains, coupled with PALB2’s role in DNA repair and Fanconi anemia, are facilitating work that is pitched at assessing the functional differences between wildtype PALB2 and PALB2 carrying rare missense mutations in key functional domains." (PMID 27099641, 2016). "Patients with biallelic truncating mutations in PALB2 have a severe form of Fanconi anaemia (FA-N), with a predisposition for developing embryonal-type tumours in infancy." (PMID 26990772, 2016). "PALB2 truncating mutations have been detected in patients with Fanconi's anemia and various cancers, including prostate." (PMID 26485759, 2015). "There have been several diseases attributed to germline mutation in PALB2, the first reports were in Fanconi anemia (FA) patients with the FA-N subtype." (PMID 24949998, 2014). "Bi-allelic mutations in PALB2 explain an unrecognised Fanconi anemia complementation group, designated subtype N (FANCN), and have been found to convey high risk of childhood cancer." (PMID 23448497, 2013). "PALB2, also known as FANCN, is a Fanconi anemia gene that encodes for a protein that interacts with BRCA2 during homologous recombination and double-strand break repair." (PMID 23586058, 2013). "Of note here is that RBS fibroblasts were less sensitive to MMC than fibroblasts from a PALB2 deficient Fanconi anemia patient, which has a more general defect in crosslink repair and shows a disturbance in the formation of Rad51 foci." (PMID 19738907, 2009). "Furthermore, it is noteworthy that bi-allelic inheritance of mutations in BRIP1, as well as BRCA2 and PALB2, contributes to the rare disease of Fanconi anemia, with patients being prone to both hematological and solid cancer development." (PMID 40988318, 2025). "The biallelic PALB2 mutation causes a new Fanconi anemia subtype, FA-N, also called FANCN." (PMID 34926254, 2021).
Fanconi anemia (continued). "Moreover, this variant has been reported to co‐occur with a second pathogenic PALB2 variant in an individual affected with Fanconi anemia." (PMID 32853479, 2020). "BRCA1, BRCA2, and PALB2 were among the genes associated with the Fanconi anemia pathway." (PMID 30719229, 2019). "Typically, inherited mutations in PALB2 are associated with a severe Fanconi Anaemia phenotype." (PMID 26990772, 2016). "A report discusses three children with Fanconi anaemia that carried a PALB2 p.Y1183X mutation." (PMID 24949998, 2014). "P/LP germline variants were recurrent in homologous recombination (n = 9; BRCA1, BRCA2, PALB2) and Fanconi anemia genes (n = 4)." (PMID 40072012, 2025). "While Fanconi Anemia-associated genes BRCA2, FANCA and PALB2 are known PCa GT candidates, FANCD2 outranked FANCA, with FANCG, ECCR4, FANCE and FANCI (in order of ranking) potential candidates." (PMID 41038821, 2025). "This recurrent PALB2 LPV identified in our cohort is particularly interesting since it was previously reported in two Fanconi anemia families with strong family history of multiple cancer types from Saudi Arabia 201629,35." (PMID 37169825, 2023). "In CRC, significant associations of HR (BRCA1, BRCA2, BARD1, PALB2 and BRIP1) and Fanconi anaemia (FANCA, FANCC and FANCG) genes with TMB were identified." (PMID 37821580, 2023). "HRR alterations involve Fanconi anemia genes (PALB2, FANCA, FANCL, FANCI, FANCC), core RAD genes (RAD50, RAD51, RAD51B, RAD51C) as well as DNA damage response genes (ATM, ATR, CHEK1, CHEK2)." (PMID 36531003, 2022). "A highlight has been given to the role of germline monoallelic variants in cancer predisposition in genes involved in the recognition and repair of DNA damage, such as the ATM, PALB2, and Fanconi anemia genes." (PMID 35495172, 2022). "As PALB2 is a Fanconi anemia gene (FANCN; OMIM #610832), the NCCN clinical practice guidelines in oncology recommend counseling PALB2 GPV carriers about the risk of autosomal recessive conditions in their offspring." (PMID 36233090, 2022). "Biallelic loss-of-function variants of PALB2 (also known as FANCN) and other BC susceptibility genes, such as BRCA2, RAD51C, and BRCA1, cause Fanconi anemia, which is characterized by a high genomic instability and increased cancer predisposition." (PMID 36139699, 2022). "PALB2 interacts with BRCA1 and BRCA2, and biallelic mutations in PALB2 (also known as FANCN), disrupts the Fanconi anemia–DNA repair pathway and increases BC predisposition." (PMID 35422484, 2022). "Among this, we found 3 mutations related to the Fanconi anemia (FA) DNA repair pathway (RMI1, PALB2, FANCI)." (PMID 34549727, 2021). "Mutations in genes that regulate DNA repair (RMI1, PALB2, FANCI) were identified that were related to the Fanconi anemia DNA repair pathway." (PMID 34549727, 2021). "The study revealed a high rate of inherited variants in patients of young ages with a wide spectrum of variants along the Fanconi anemia pathway (BRCA1, BRCA2, and PALB2)." (PMID 33646313, 2021). "BRCA2 acts as a platform to form multimeric structures–it not only directly binds to RAD51 but also to Partners with Localizer of BRCA2 (PALB2/FANCN) and Fanconi Anemia (FA) Complementation Group D2 (FANCD2)." (PMID 33043007, 2020). "Overall, 14.6% had mutations in BRCA1 or BRCA2, 3.3% had mutations in other BRCA–Fanconi anemia genes (BRIP1, PALB2, RAD51C, RAD51D, BARD1), and 0.4% had mutations in mismatch repair genes linked to Lynch syndrome." (PMID 32679669, 2020). "qRT-PCR data confirmed that the expression of Fanconi anemia-associated genes including BRCA1, BRCA2, PALB2, and RAD51 and cancer-associated genes (ALDH1A3 and IGF1R) was strongly inhibited by FR treatment, as shown by microarray analysis." (PMID 30719229, 2019).